CXCL8 (C-X-C motif chemokine ligand 8)
Diseases named in the same sentence as CXCL8 in open-access papers (continued):
Sharing a sentence is not in itself a finding about the gene and the disease.
tumor (continued). "They accomplish this through the increased expression of IL‐6 and CXCL8, which support M2 macrophage polarization, and TGF‐β, which facilitates the recruitment and retention of macrophages in the TME and enables effective tumor evasion of the host immune system." (PMID 39928309, 2025). "Additionally, CCL20 and CXCL8 secreted by tumor cells into the tumor microenvironment (TME) were found to promote the recruitment of Treg cells and reduce CD8+ T cell infiltration, thereby facilitating tumor immune evasion." (PMID 40463392, 2025). "For several solid tumors with high levels of CXCL8, including pancreatic, breast, and ovarian cancer cells, enforced expression of CXCR1 or CXCR2 in A20-28z CAR-T cells showed a higher infiltration proportion in the tumor core, with altered specificity or cytolytic activity." (PMID 40148310, 2025). "Furthermore, there is emerging evidence of the co-expression of TIMP1 with both CXCL8 and c-MYC, which may influence PD-L1 expression and thus, the immune escape mechanisms of tumor cells." (PMID 40290432, 2025). "CXCL8 levels are greater in the tumor tissue of HNSCC patients than in normal tissue, and the survival time of patients with high CXCL8 mRNA levels was shorter in TCGA data; moreover, CXCL8 was highly correlated with the infiltration of macrophages and clinical pathological stage in TCGA data." (PMID 39905539, 2025). "Similarly, after co-incubation with PLIGHT- or PαCD3&LIGHT-transfected tumor cells, the mRNA levels of chemokines and vascular adhesion molecules in vascular endothelial cells, such as CXCL-2, CXCL-8, CXCL-12, CCL-21, MADCAM-1, and VCAM-1, rose by about 2- to 5-fold." (PMID 41406950, 2025). "Under normal physiological conditions, CXCL8 is barely detectable; however, within the TME, it rapidly accumulates to effectively regulate the protumor effects of N2 neutrophils, including the promotion of angiogenesis, dedifferentiation, and metastasis of tumor cells." (PMID 39925807, 2025). "Additionally, the characteristic expression profile of this cell subgroup included multiple myeloid cell activation markers, such as IL1RN, CXCL8, CCL20, and the chemokines CCL3 and SPP1, indicating the activated state of myeloid cells in the tumour microenvironment." (PMID 40539065, 2025). "Our study did not distinguish whether CXCL8 was produced by tumor cells or immune infiltrates, which remains a limitation." (PMID 41432874, 2025). "G31P is a synthetic form of CXCL8 with modifications in lysine to arginine (K11R) and glycine to proline (G31P) substitutions, which confer potent CXCR1/2 antagonism, thereby blocking ELR+ CXC chemokines signaling pathways involved in tumor growth, neutrophil infiltration, and resistance to therapy." (PMID 41425704, 2025). "For example, both CXCL8 and CCL2 promote the production of inflammatory mediators and the recruitment of immune cells through the activation of the NF-κB pathway, which enhances the inflammatory microenvironment of tumors and the resistance of tumor cells to apoptosis." (PMID 38791448, 2024). "Interleukin-8 (IL-8, CXCL8), which was originally discovered as a neutrophil chemoattractant and inducer of leukocyte-mediated inflammation, plays a crucial role in cancer progression through its induction of tumor cell proliferation, migration, invasion, angiogenesis and metastasis." (PMID 39123403, 2024). "In addition, CXCL8 exhibited a tenfold increase in expression in tumor samples compared to non-neoplastic counterparts in 76% of patients." (PMID 38979413, 2024). "CXCL8, besides being a neutrophil chemotactic factor, also acts on endothelial cells and exerts angiogenic activity in the tumor microenvironment, suggesting that SKAP1 may promote tumor progression through the CXCL8‐dependent regulation of angiogenesis." (PMID 39269257, 2024).
tumor (continued). "APOC1 is primarily expressed in tumor cells and macrophages and shows a positive correlation with the expression of genes such as CD68, CD86, CD163, CXCL17, CXCL8, and IL-10, suggesting that APOC1 may promote tumor progression by influencing macrophage polarization." (PMID 39877420, 2024). "TAMs promote tumor angiogenesis by secreting a plethora of pro-angiogenic growth factors, cytokines, and chemokines that induce EC proliferation and migration, including EGF, FGF-2/bFGF, platelet-activating factor (PAF), PDGF, VEGF, TNF-α, IL-1, IL-8/CXCL8, and CCL18." (PMID 38580870, 2024). "Additionally, CXCL8 can be involved in the proliferation, self-renewal, and recruitment of CXCR1/CXCR2-expressing cancer stem cells, which are known to promote tumorigenesis, tumor maintenance, metastasis, and drug resistance in many different cancers." (PMID 36725964, 2023). "Results showed that tumor cells usually have negative CXCL8 staining." (PMID 37765018, 2023). "NF-κB signalling also contributes to tumour progression and invasion by controlling pro-angiogenic genes such as vascular endothelial growth factor (VEGF) and its receptors, macrophage inflammatory protein-1 (MCP-1) and CXC-chemokine ligand 8, also known as IL-8 (CXCL8)." (PMID 36899924, 2023). "In addition to the cytotoxic effects inducing the apoptosis of immune cells residing in the TME, a reduced production of inflammatory factors such as CCL2, CXCL8, and VEGF was observed, resulting in a diminished migration of tumor-promoting immune cells, including MDSC, to the TME." (PMID 37513979, 2023). "IL-8 or CXCL8 also increases during the period of transition from normal tissue to polyp size ≤ 2 cm, while CXCL7 increases at polyp size > 2 cm, suggesting that these could become potential cancer biomarkers of every tumor stage." (PMID 38068961, 2023). "Moreover, RNA-seq results showed that NAT10 promoted the transcription of multiple critical cytokines such as CXCL3 and CXCL8 and suppressed CXCL10, CXCL11 and so on, which are important for the recruitment of immune cells, angiogenesis, tumor microenvironment remodeling, and cancer progression." (PMID 37914704, 2023). "CXCL8 and CDK1 may change G2-M transformation and EMT and promote tumor proliferation." (PMID 36078096, 2022). "Besides, critical chemokine ligand family members (including CXCL1, CXCL2, CXCL5, CXCL8, and CXCL11), which involved in tumor growth regulation and metastasis and mediated the enrichment of CD8+ T cells into the TME, were upregulated in the high AI score subtype." (PMID 36245985, 2022). "However, CXCL8, which promoted tumor invasion and angiogenesis, was not significantly down-regulated in the high-GATA3 group." (PMID 35647011, 2022). "Furthermore, NGS analysis revealed that NF-κB/RELA targets including CCL2, CXCL8, EDN1, IL-1β, IL-6, and SERPINE1 were further reduced and several potential tumor suppressors, such as FABP3, FADS2, FDFT1, SEMA6A, and PCK2, were synergistically induced by the Gefitinib-+IKK16 treatment." (PMID 36358633, 2022). "In this context, interleukin-8 (IL-8, aka CXCL-8), a member of the CXC chemokine family that is highly produced by neoplastic cells, is an important chemoattractant and activator for neutrophils and is a key mediator of their biology, behavior and actions inside the tumor." (PMID 36591453, 2022). "Therefore, our study aimed to detect the serum level of CXCL-8 in patients with CRC and compare this chemokine to current tumor markers to establish whether it may be considered an improved tumor marker for CRC diagnosis." (PMID 36567905, 2022). "Among tumor-related factors involved in the generation of MDSCs and their recruitment from bone marrow to tumor microenvironment are mediated by granulocyte–macrophage colony-stimulating factor (GM-CSF), IL-6, indoleamine 2,3-dioxygenase (IDO) and chemokines (e.g. CCL26, CXCL12, CXCL8)." (PMID 35589776, 2022).
tumor (continued). "Interleukin‐8 (IL‐8), a CXC chemokine and also known as CXCL8, was initially described as an inflammatory innate immune response mediator and subsequently shown to be a potent angiogenic factor leading to tumour progression and metastasis in various human cancers." (PMID 35770335, 2022). "Furthermore, the ROC curve analysis showed that hub gene (CXCL8, DDX60, IFI44L, RSAD2, and RTP4) could distinguish OC from normal tissues, and the diagnosis effect of tumor tissue was better, and the combined diagnosis of five genes was the best." (PMID 34384424, 2021). "Moreover, AUC for CXCL8 was higher than for CXCR2 and classical tumor markers." (PMID 34680333, 2021). "Also, blocking the CXCL8 and its receptors (CXCR1 / CXCR2) appears to be a novel therapeutic strategy that may reverse the tumor cell metastatic phenotype in patients with ESCCs." (PMID 33390169, 2021). "M2-like macrophages promote tumor angiogenesis by producing proangiogenic growth factors (VEGF-A, epidermal growth factor (EGF), and fibroblast growth factor (FGF)), proangiogenic CXC chemokines (CXCL8/IL-8 and CXCL12), and angiogenesis-related factors (TGF-β and TNF-α)." (PMID 34294146, 2021). "In humans, Interleukin-8 (IL-8 or CXCL8) is a granulocytic chemokine with multiple roles within the tumor microenvironment (TME), such as recruiting immunosuppressive cells to the tumor, increasing tumor angiogenesis, and promoting epithelial-to-mesenchymal transition (EMT)." (PMID 35011369, 2021). "Contrastingly, basophils may exert pro-tumor activities, through release of pro-angiogenic and lymphangiogenic mediators, such as VEGF-A and VEGF-B, CXCL8, angiopoietin-1, hepatocyte growth factor, and tryptase, and may suppress anti-tumoral immune responses, such as through T-reg interactions." (PMID 32645919, 2020). "Therefore, the synergistic effect of CXCL8 and VEGF can promote tumour angiogenesis." (PMID 32201645, 2020). "Manfroi in a recent work demonstrated that in a significant fraction of DLBCL patients, tumor cells are able to recruit APRIL producing neutrophils through the release of CXCL8 in both GC and non-GC DLBCL subtypes that in turn induce DNA methylation and acetylation, crucial in DLBCL progression." (PMID 32731512, 2020). "When we considered correlations between the clinicopathological features of the tumor and serum levels of the tested proteins in relation to the histological type of OC, we found a positive correlation only between serum CXCL-8 levels and CRP concentrations (p = 0.021) (data not shown)." (PMID 30820705, 2019). "Importantly, we found that CXCL8 was a key regulator of the pro-metastatic activities that came into play in the TNBC-stroma-inflammation networks, including angiogenesis, metastasis-related morphology, tumor cell migration and invasion of TNBC cells." (PMID 31031757, 2019). "Using siRNA to CXCL8, we found that CXCL8 was significantly involved in mediating the pro-metastatic activities gained by TNFα-stimulated TNBC:MSC “Contact” co-cultures: angiogenesis, migration-related morphology of the tumor cells, as well as cancer cell migration and invasion." (PMID 31031757, 2019). "In a recent study we identified a tumor-stroma-inflammation network potentiating multiple processes that contribute to increased metastasis in TNBC; they included expression of pro-metastatic chemokines such as CXCL8 and CCL5, angiogenesis and tumor cell migration and invasion." (PMID 31105691, 2019). "Despite the fact that TNFα and IL-1β induced potent p65 and JNK activation in T47D and MCF-7 luminal-A cells, CXCL8 levels were not increased but rather were decreased when the tumor cells interacted with MSCs in the presence of TNFα and IL-1β (Figures 6B1, 7B)." (PMID 31031757, 2019).
tumor (continued). "The assessment of the relationship between the tested protein concentrations, the clinicopathological parameters and TNM stage of OC revealed that serum CXCL-8 concentrations increased with tumor stage, although these differences were not statistically significant." (PMID 30820705, 2019). "Moreover, under resting conditions and/or as a consequence of proinflammatory stimuli, transformed thyrocytes produce and release inflammatory factors such as CXC chemokines (e.g., CXCL1, CXCL8, CXCL9, and CXCL10), which promote the recruitment and activation of tumor-infiltrating leukocytes." (PMID 29953504, 2018). "First, increasing neutrophils can promote tumor growth and invasion by releasing the vascular endothelial growth factor (VEGF), series of inflammatory mediators including angiogenesis circulating chemokines (CXCL8), matrix metalloproteinase-8/9 and the anti-apoptotic factor, nuclear factor-κB30,31." (PMID 30413724, 2018). "Thus, we assessed whether increases in TNF-α, CXCL8, and CXCL1 would also be observed during selection of tumor cells for survival in increasing concentrations of docetaxel." (PMID 28915246, 2017). "Moreover, HCC-stimulated MSCs could enhance the recruitment of other cells to the tumor milieu, probably through the secretion of chemokines such as CXCL8/IL-8, CXCL1-2-3/GRO and CXCL6/GCP-2." (PMID 29113298, 2017). "Elevated expression of CXCL8 correlates with angiogenesis and VEGF expression in endothelial cells, an increase of proliferation and survival, an increase of migration of cancer cells, an induction of neutrophils on the tumor site, with tumorigenesis and metastasis in vivo models." (PMID 26859141, 2016). "Of interest, a previous report indicated that expression of CXCL8 might preserve the angiogenic response in HIF-1-inhibited tumor cells, suggesting that the NFκB pathway is important for the induction of CXCL8 in the absence of HIF-1α." (PMID 26696754, 2015). "Here, eight hours following stimulation by TNFα, the medium of the cells was exchanged to TNFα-deficient medium, and following additional 36 hr of cell growth, CM that were enriched in tumor-promoting factors such as CXCL8 (data not shown) were collected and injected to tumors." (PMID 24598028, 2014). "An example of such differences might be the prominent role that CXCL8 has in the crosstalk between endothelial cells and tumor cells and the well-known absence of this protein in murine cells." (PMID 24391922, 2013). "We have previously identified IL-1α to be the main tool used by the tumor cells to activate CAFs to produce several inflammatory factors (e.g., IL-6, CCL20, CXCL8, COX-2, and VEGF-A), and this could be one mechanism the tumor cells use to escape elimination by the immune system." (PMID 22190968, 2011). "The surgical removal of the tumor mass decreased the CXCL8 and PGE2 levels but not to normal levels, which could explain why the partial DC maturation was not reversed." (PMID 20976171, 2010). "Studies have demonstrated that TANs may promote tumor angiogenesis by inducing sustained release of vascular endothelial growth factor (VEGF) from peripheral endothelial cells or by secreting pro-inflammatory and immunosuppressive factors, such as IL-1β, IL-17, TNF-α, CCL4, MMP-9, CXCL8, and ANG1." (PMID 40563367, 2025). "Therefore, to help improve tumor trafficking to tumor tissues, in the studies reported here we also evaluated the impact of addition of a chemokine receptor (CXCR2) to the CAR construct, to enhance trafficking to a CXCL8 gradient, which is present in many tumor types." (PMID 38554158, 2024).
tumor (continued). "Tryptophan metabolizing enzymes can accelerate tumor progression by upregulating CXCL8, which is also a chemokine in the IL-17 signaling pathway, and CXCL8 has a high degree value in PPI network; hence, we speculate that CXCL8 could be a potential target in the treatment of PitNETs." (PMID 39295931, 2024). "Therefore, one could speculate that both markers, CCL20 and CXCL8, discriminate advanced tumor stages rather than detecting early HCC and predict poor prognosis." (PMID 36982370, 2023). "Beyond its effects on chemotaxis, CXCL8 can also have a major influence on neutrophil functions in ways that, at least theoretically, might have either positive or negative implications for tumor progression." (PMID 37444436, 2023). "In addition, CXCL8 may directly stimulate CXCR1- or CXCR2-expressing tumor (microenvironmental) cells, stimulating their survival, proliferation, and migration further enhancing tumor expansion." (PMID 36725964, 2023). "Indeed, the tumor cores (L and LB) were found to express numerous pEMT genes at significantly greater levels than the TME, including the laminins (LAMC1, LAMC2, LAMA3), integrins (ITGA2, ITGB1, ITGAV), and inflammatory and neutrophil-attracting chemokines (CXCL8, CXCL1)." (PMID 36216799, 2022). "From data acquired thus far, we hypothesise that CXCL8 is involved in promoting a stroma‐rich microenvironment which aids tumour immune evasion and EMT, and that targeting this pathway could be therapeutically beneficial in a subset of patients with right‐sided tumours." (PMID 35879507, 2022). "However, it needs to be remembered that the mechanisms mentioned in this paragraph are not necessary for the induction of CXCL8 expression in tumor cells by chronic hypoxia and that they only enhance the influence of chronic hypoxia in terms of the expression of this chemokine." (PMID 33467722, 2021). "Consistent with this, we found all angiogenesis-related genes to be significantly upregulated in non-pCR patients, with VEGFA, CXCL8, CXCL2, CXCL3, and HBEGF identified as core drivers of tumor angiogenesis and immune escape." (PMID 41514936, 2026). "The comparison of tumor tissue (TU) and adenomatous polyp tissue (TU) highlights that the expression of CXCL1, CXCL8, and PTGS2 does not differ significantly (adj." (PMID 38979413, 2024). "Although our study emphasizes the crucial role of the CXCL8‐NET axis, we cannot rule out other mechanisms involved in SKAP1‐induced tumor promotion." (PMID 39269257, 2024). "Raychaudhuri and Vogelbaum discovered that in GBM, the tumor cells do not express CXCR2; they only express CXCR1 while also expressing CXCL8." (PMID 36831112, 2023). "The current study highlights the importance of the spatial distribution of CXCL8 expression within the TME, as stromal but not tumour cell CXCL8 expression was significantly prognostic." (PMID 35879507, 2022). "Intriguingly, these observations were almost further validated by our real‐time qPCR results of five pairs of tumor and adjacent nontumor samples, such as COL1A1, MMP1, MMP10, CXCL8, and IL1B." (PMID 34821009, 2022). "Tumour-promoting inflammatory factors, including IL-6, LIF, and CXCL8, are mainly secreted by iCAFs but not myCAFs." (PMID 36284087, 2022). "Pre-incubation with 1 μg/ml anakinra dramatically reduced the production of CXCL8 and CCL2 but not CCL5 for both UPCI-SCC90 and FaDu 3D tumour-stromal models." (PMID 35047989, 2021). "Our data indicate that without TNFα stimulation, CXCL8 produced in TNBC:MSC co-cultures was released exclusively by the tumor cells and resulted from basal p65 activation in the tumor cells." (PMID 31105691, 2019). "To this end, we have analyzed the expression of CXCL8 in TNFα-stimulated and non-stimulated MDA-MB-231:MSC co-cultures in which Notch1 was down-regulated by siRNA in the tumor cells." (PMID 31105691, 2019).